IL1B (interleukin 1 beta)
Diseases named in the same sentence as IL1B in open-access papers (continued):
Sharing a sentence is not in itself a finding about the gene and the disease.
iron deficiency (20 papers, 2010 to 2025). "IL-1β (4.94 pg/mL for iron sufficiency, 8.09 pg/mL for iron deficiency, p = 0.029), and IL-7 were higher in iron deficiency patients (0.19 pg/mL for iron sufficiency, 0.39 pg/mL for iron deficiency, p = 0.014)." (PMID 39898042, 2025). "This study aimed to evaluate the usefulness of the IL1B single-nucleotide polymorphism (SNP) (rs1143634) and plasma concentration of IL-1β in the assessment of the risk of nutritional disorders and prognosis in patients with MM." (PMID 38610941, 2024). "It should be emphasized that in the literature, there are no studies describing the association of SNPs of genes encoding proinflammatory cytokines, including those located within IL1B, in particular rs1143634, with the risk of nutritional disorders in MM." (PMID 38610941, 2024). "Iron deficiency, erythropoietin treatment or interleukin-1 beta (IL-1β) stimulate FGF23 production by osteocytes and bone marrow hematopoietic cells." (PMID 34149625, 2021). "The correlation between hepcidin and IL-1β expression has been previously reported in humans with iron deficiency." (PMID 33849522, 2021). "The iron deficiency and the pro-inflammatory cytokines/inflammation (IL-6, IL-1β and TNFα) act as positive regulators." (PMID 31172340, 2019). "In conclusion, high gastric levels of IL-1β can be the link between H. pylori infection and iron deficiency/iron deficiency anaemia in childhood." (PMID 23451225, 2013). "While levels of TNF, IFN-γ and IL-1β (type I) and IL-10 and IL-13 (type II) seemed decreased in iron deficiency anaemia, the levels of IL-12 and IL-5 appeared increased." (PMID 20546583, 2010). "In the present study, we demonstrated that iron deficiency led to an enhanced pro-inflammatory response, resulting in a marked increase in serum contents of the inflammatory cytokines, IL-1β, IL-4, IL-6, TGF-β1, and TNF-α and a trend towards increased contents of IL-12 and GM-CSF." (PMID 39296492, 2024). "Iron deficiency may also result in chronic inflammation as an effect of the action of proinflammatory cytokines (IL-6, IL1β, and IL-22), and finally increase hepcidin expression." (PMID 35160288, 2022). "Magnesium deficiency in a rat model of endotoxin shock also promoted the secretion of proinflammatory cytokines, including interleukin-6, tumor necrosis factor-alpha, and interleukin-1-beta, which intensify the failure of various organs." (PMID 36424547, 2022). "Under conditions of iron deficiency furin is responsible for this process, while following single injection of rhEPO or IL-1β, additional proteases may be involved in FGF23 processing." (PMID 34149625, 2021). "Thus, in vivo iron status modulates the immune responses, dietary iron deficiency exacerbated pro-inflammatory effects of endotoxin whereas dietary iron loading decreased some inflammatory responses such as Il-1β expression." (PMID 29771935, 2018). "The findings may reflect that magnesium deficiency is associated with an increase in IL-12 and IL-1β but these responses become weakened in malaria infection." (PMID 20546583, 2010). "In this study, iron deficiency also decreased the levels of inflammatory factors such as TNF-α, IFN-γ, IL-6 and IL-1β in the serum of neonatal pigs." (PMID 39127747, 2024). "The mRNA expression of the endometrium receptivity-related genes, PR, SOX-17, CX3CR1, FKN, activin, follistatin, BMP2, as well as the examined cytokines and chemokines LIF, IL-6, and IL-1β, were significantly downregulated at DFO-induced iron deficiency in HEC-1A cells." (PMID 37175630, 2023). "Oral application of L-TAMS substantially reversed the magnesium deficiency and upregulation of TNF-α/NF-κB signaling and IL-1β and normalized the expression of NR2B." (PMID 32241292, 2020). "Magnesium deficiency seemed to be associated overall with low TNF concentrations, low concentrations of IL-1β and higher concentrations of IL-10 in uninfected but not infected donors." (PMID 20470442, 2010).
leishmaniasis (20 papers, 2012 to 2025). Infectious disease that is transmitted through the bite of hematophagous female phlebotomine sand flies. "In conclusion, our data show that leishmaniasis patients with IL-1β polymorphism have a heightened risk to develop the disease." (PMID 22629474, 2012). "Furthermore, both inflammasome activation and IL-1β have been associated with disease severity in leishmaniasis." (PMID 34691019, 2021). "IL-1β promotes the development of leishmaniasis in L. major infected susceptible BALB/c mice." (PMID 31134162, 2019). "Furthermore, both inflammasome activation and IL-1β have been linked with disease severity in leishmaniasis, suggesting that CD8+ T cell cytotoxicity might increase inflammasome activation and IL-1β production, thereby driving disease severity." (PMID 28192528, 2017). "During leishmaniasis, IL-1β production triggers Inducible Nitric Oxide Synthase (iNOS) activation and Nitric Oxide (NO) production, which are responsible for parasite clearance." (PMID 40142422, 2025). "Pro-inflammatory cytokines such as IL-1β, IL-6, TNF-α, and IFN-y have been associated with resistance in leishmaniasis." (PMID 38241360, 2024). "We observed that the decrease in miR-194 activity in PBMCs from dogs with leishmaniasis increased NO and IL-1β in the culture supernatants." (PMID 38241360, 2024). "PBMCs from dogs with leishmaniasis were transfected with miR-194 inhibitor with IL-1β blocking antibody." (PMID 38241360, 2024). "We demonstrated that an increase in miR-194 activity increases parasite load, and its inhibition increases IL-1β and NO in PBMCs from dogs with leishmaniasis." (PMID 38241360, 2024). "Further, the expression of key cytokines involved in leishmaniasis-mediated inflammation, including IL-1β, IL-10, IL-12 and TNF-α, remained constant across all experimental groups." (PMID 39076982, 2024). "Regarding the pro-inflammatory cytokines IL-1β, IL-6, TNF-α, and IFN-y, only IL-1β increased in PBMC culture supernatants from dogs with leishmaniasis after transfection with the miR-194 inhibitor." (PMID 38241360, 2024). "By contrast, there was an increase in IL-1β following a decrease in miR-194 activity in the supernatant of PBMCs from dogs with leishmaniasis." (PMID 38241360, 2024). "Still, our data demonstrated an overall increased expression of inflammasome-related genes such as Gsdmd, Nlrp3, Casp1, Casp4, Il1b, Ifng, Tnfa, Il10, and Il17a when we compared Leishmaniasis patients with controls." (PMID 36828815, 2023). "Our results are consistent with studies indicating an important role for IL-1β in several models of IL-17-mediated disease, and suggest that IL-1 plays a critical role in inducing IL-17 mediated pathology in leishmaniasis." (PMID 23555256, 2013). "The expression level of IL-1β by epidermal keratinocytes is one of the decisive factors for generating protective Th1 immunity during experimental Leishmaniasis, along with IL-12, IL-4, IL-6, and osteopontin." (PMID 23286586, 2013). "In contrast to patients with leishmaniasis, controls showed only minimal amounts of IL-1β (lanes 1–4)." (PMID 22629474, 2012). "Recent advances in research have indicated crucial role for NLRP3 inflammasomes during Leishmaniasis.NLRP3 inflammasomes exert strong control over IL-1β and IL-18 production, and these cytokines are considered key mediators during Leishmania infections both in vitro and in vivo." (PMID 38623843, 2024). "In another study aiming to understand the role of the NLRP3 inflammasome in Th1/Th2 responses during leishmaniasis, knockout BALB/c mice for NLRP3, ASC, or caspase-1, displayed deficient IL-1β and IL-18 production and were resistant to cutaneous L. major infection." (PMID 38623843, 2024). "In experimental leishmaniasis, mice lacking IL-1a or IL-1b displayed delayed disease development and more attenuated systemic inflammatory responses, while IL-1b has been associated with immunopathology in human CL caused by L. braziliensis." (PMID 38787268, 2024).
leishmaniasis (continued). "miR-194 inhibition increased IL-1β and NO production in PBMCs from dogs with leishmaniasis." (PMID 38241360, 2024). "Here, using studies in mice and experiments with L. braziliensis patients’ samples we show that increased disease severity is due to inflammasome activation, and furthermore that therapies that block either inflammasome activation or IL-1β ameliorate disease in mouse models of severe leishmaniasis." (PMID 28192528, 2017). "The differential kinetics of Acod1 and Il1b expression in L. major-infected BMDMs may support the hypothesis that itaconate contributes to the progression of leishmaniasis by inhibiting M1 macrophage polarization and potentially driving an M2-mediated response." (PMID 40142422, 2025). "Therefore, we propose that regulating IL-17, possibly by downregulating IL-1β, may be a useful approach for controlling immunopathology in leishmaniasis." (PMID 23555256, 2013). "Test for a possible regulatory role of miR-194 in the production of cytokines IL-1β, IL-6, IL-4, TNF-α, IFN-y, TGF-β, and IL-10, PBMCs from healthy dogs and those with leishmaniasis were transfected with miR-194 Mimic and Inhibitor." (PMID 38241360, 2024). "Leishmaniasis induced significant increase of spinal cord GFAP, Iba-1, TNF-α, IL-1β, CX3CR1, and CX3CL1 mRNA expression, which were inhibited by α-aminoadipate, minocycline, and PDTC treatments (p < 0.05)." (PMID 31138231, 2019). "Confirming the relevance of these findings to human leishmaniasis, blockade of the NLRP3 inflammasome in skin biopsies from leishmania-infected patients prevented IL-1β release." (PMID 28192528, 2017). "The analysis of IL-1β and other proteins that participate in inflammation like caspase-1 and -5 or NALP3, in a larger group of patients, could possibly help define to what extent polymorphisms and enhanced production of IL-1β contribute to various clinical forms of leishmaniasis." (PMID 22629474, 2012). "By employing two different murine models of infection, we found that CD8+ T cell-induced pathology depended on the NLRP3 inflammasome and IL-1β signaling, and demonstrated that the NLRP3 inflammasome is required for the high levels of IL-1β present within lesions of leishmaniasis patients." (PMID 28192528, 2017).
liver failure (20 papers, 2012 to 2024). A liver disease characterized by the liver losing or has lost all of its function. "An IL-1β pretreatment improved the homing efficacy of mesenchymal stem cells on liver failure through an increased CXCR4 expression." (PMID 36979628, 2023). "The inflammatory factors that have been reported to be associated with poor prognosis of liver failure include TNF-α, IL-1β,and IL-6, etc.." (PMID 37649110, 2023). "Another study on rats has shown that the reduced serum level of IL-1β promoted liver regeneration after liver failure." (PMID 33987145, 2021). "In D-gal/LPS-induced liver failure, loss of ATG5 significantly increased IL-1β expression, with massive infiltration of neutrophils and aggravated liver failure." (PMID 34930917, 2021). "The serum level of HDAC2, IL-18, and IL-1β in liver failure patients was higher than healthy donors." (PMID 33431796, 2021). "Previous studies have persistently reported the activation of microglia cells, increased inflammatory factor levels (e.g., TNF, IL-6, and IL-1β), Alzheimer's type II astrocytosis, and neuronal cell death in patients with liver failure." (PMID 32256557, 2020). "TNF-α and IL-1β, the two major pro-inflammatory cytokines, stimulated the matrix metalloproteinases, and ultimately resulted in liver failure." (PMID 29723988, 2018). "Additionally, IL-1β plays a critical role in hepatic failure via NF-κB signaling and proinflammatory cytokine activation." (PMID 36899958, 2023). "Therefore, neutralizing IL-1β in the serum of dead ACLF patients may improve the efficacy of hUC-MSCs on liver failure." (PMID 37649110, 2023). "Moreover, we have suggested the activation of related signaling transduction could induce Bcl-2 expression and inhibit Bad, TNF-α and IL-1β expression, which could ameliorate the apoptosis and necrosis of hepatocytes to prevent the liver failure." (PMID 32483425, 2020). "Thus, higher levels of TMAO and TNFa/IL6/IL1b levels could lead to a synergistic feedback loop in liver failure." (PMID 29844325, 2018). "The high level of IL-1β in the serum of dead ACLF patients can promote the expression of IL-8 in hUC-MSCs, thereby reducing the therapeutic effect of hUC-MSCs in liver failure." (PMID 37649110, 2023). "Therefore, the level of inflammatory factors (such as a high level of IL-1β) in liver failure patients can affect the efficacy of stem cells, but improving the inflammatory environment in liver failure patients prior to the application of stem cell therapy may improve the efficacy of stem cells." (PMID 37649110, 2023). "Together, these data indicate that CCR2 and CCR4 signaling are required for microglia activation and subsequent production of the proinflammatory cytokines IL-1β and IL-6 following AOM-induced liver failure." (PMID 25012628, 2014). "Treatment with L. sativum and tadalafil, either alone or in combination, resulted in a significant (p < 0.0001) decrease in IL-1β and TNF-α levels in the liver tissue when compared to the CCL4-induced liver failure group, with a possibly superior effect for the tadalafil-L." (PMID 38413963, 2024). "The high level of the inflammatory factor IL-1β in serum from ACLF patients can promote the expression of IL-8 in hUC-MSCs through the NF-κB signaling pathway, thereby reducing the effect of hUC-MSCs in the treatment of liver failure." (PMID 37649110, 2023). "From the clinical study, the high serum levels of HDAC2, IL-18, IL-1β were found in liver failure patients, when compared with normal subjects." (PMID 33431796, 2021). "Studies have documented, in HE patients and rodent models with liver failure, the activation of microglia and hepatic macrophage, together with increases in pro-inflammatory factors, including tumor necrosis factor alpha (TNF-α), interleukin-1 beta (IL-1β), and interleukin-6 (IL-6)." (PMID 38725082, 2024).
metastatic tumors (20 papers, 2012 to 2025). "There is now evidence that targeting the AR causes cancer cells to secrete IL-1β, an inflammatory molecule with a recognized role in promoting the growth and survival of cancer cells in metastatic tumors." (PMID 39858071, 2025). "Similar studies also demonstrated that IL-6, a downstream mediator of the IL-1β, induced expansion of MDSCs, and IL-1 receptor (IL-1R)-deficient mice have a delayed accumulation of MDSCs and delayed primary and metastatic tumor progression." (PMID 33014771, 2020). "With this main objective in mind, we start by discussing the pro-tumoral properties of IL-1β produced and secreted by immune cells and promoting the growth of primary and metastatic tumors." (PMID 39858071, 2025). "Our data showed that EVs from OCs with PCa cells induce further OC activation while concurrently suppressing OB function by mediating IL‐1β‐related reactions, leading to further bone destruction and metastatic tumour progression." (PMID 40545975, 2025). "IL-1β expression was significantly higher in the plasma of patients with metastatic disease from the mixed cohort (p = 0.022)." (PMID 41008853, 2025). "Several studies have demonstrated that pro-inflammatory cytokines such as IL-1β, IL-6 and IL-8 are higher in metastatic tumors and indicate poor survival in various cancer patients [34, -36]." (PMID 37501379, 2023). "We chose to block IL-1β to test the role of pyroptosis on immune infiltration and metastatic tumor progression." (PMID 31685946, 2020). "Significantly higher levels of the pro-osteoclastogenic cytokines IL-17F,RANKL, IL-1β, TNFα, and IL-6 were detected in the sera and supernatants fromLN-stimulated cells of animals bearing the metastatic tumors than in mice withnon-metastatic tumors." (PMID 23935856, 2013). "Interestingly, in the “mixed cohorts” patients, those who presented with metastatic disease had a higher median level of IL-1β than those presenting with localized disease (1.23 pg/mL vs. 1.10 pg/mL; p = 0.022)." (PMID 41008853, 2025). "Biomarkers like IL-6, IL-8, IL-1β, and IL-11 offer opportunities for early detection, patient stratification, and personalized treatment approaches, enhancing the clinical management of metastatic disease." (PMID 39125732, 2024). "The NLRP3 inflammasome increased the recruitment of CD11b+Ly6ChighLy6G− myeloid cells into tumors, and IL-1β increased the recruitment of the granulocytic fraction (CD11b+Ly6G+Ly6Clow) in the primary tumor and the monocytic fraction (CD11b+Ly6ChighLy6G−) in metastatic tumors." (PMID 35739593, 2022). "The first is the capacity of Everolimus to restrain the progression of skeletal metastatic disease in BC patients through a specific mechanism that includes inhibiting the release by these cells of the most effective pro-OC factors such as M-CSF, TNFα, IL-1β, IL-6, MIP-1α and MMP-13." (PMID 26468083, 2015). "More importantly, knockdown of the expression of IL1α, IL1β and IL8 significantly reduced the size of metastatic tumors in the iliac lymph nodes by 81.9%, 68.0%, and 78.5%, respectively." (PMID 37551997, 2023). "The results showed that the protein levels of IL-1b and TNF-a in the hepatocyte co-culture+IL-6 treated LUADs derived metastatic tumor were dramatically elevated, whereas significantly decreased in the hepatocyte co-culture+Peptide 17 treated LUADs." (PMID 33495421, 2021). "In this report, we investigated the role of the inflammatory cytokine, IL-1β, in RCC tumor cell invasiveness as a key characteristic of a tumor cell's progression to metastatic disease." (PMID 23342250, 2012). "In a highly plausible model, AR-negative cancer cells inhabiting metastatic tumors secrete IL-1β and the signaling by this cytokine elicits the production of tumor-promoting factors by the surrounding stromal cells via IL-1R stimulation." (PMID 39858071, 2025). "Moreover, we evaluated the protein level of two inflammatory cytokines (IL-1b and TNF-a) in the metastatic tumors." (PMID 33495421, 2021).
Multiple Organ Failure (20 papers, 2012 to 2026). A progressive condition usually characterized by combined failure of several organs such as the lungs, liver, kidney, along with some clotting mechanisms, usually postinjury or postoperative. "IL-1β, another pro-inflammatory cytokine, causes multiple organ failure associated with endotoxic shock." (PMID 37024954, 2023). "IL17A, IL1B, MBL, and NOD2 were also reported to be associated with mortality, and PPARG was associated with multiple organ failure in our study." (PMID 40168842, 2025). "This activation triggers inflammatory gene expression characterized by excessive cytokine release, including tumor necrosis factor-alpha, interleukin-1 beta, and interleukin-6, ultimately resulting in widespread tissue damage, increased vascular permeability, and multiple organ failure." (PMID 40941711, 2025). "These previous studies, including ours, support the present findings of the role of IL-1β in trypsin upregulation in combination with IL-6 and/or TNF-α, and also on the role of trypsin in the induction of various signal transductions in multiple organ failure." (PMID 27714503, 2017). "Clinical studies revealed that the levels of TNF-α, IL-1β, and IL-6 in BALF and plasma of patients with ALI/ARDS increased and were correlated with the pathogenesis of multiple organ failure." (PMID 23586067, 2013). "Previous studies have demonstrated that the expression of iNOS is stimulated by proinflammatory cytokines, including IL-1β and TNF-α, which contribute to tissue damage and multiple organ failure." (PMID 23573152, 2013).